NEGR1 (neuronal growth regulator 1)
Description:
May be involved in cell-adhesion. May function as a trans-neural growth-promoting factor in regenerative axon sprouting in the mammalian brain (By similarity).
Synonyms: IGLON4; KILON; MGC46680; Ntra; DMML2433
Tractability: Antibody: its Gene Ontology location is reachable by antibodies, with high confidence; UniProt places it where antibodies can reach, with medium confidence; UniProt predicts a signal peptide or a membrane-spanning region. PROTAC: ubiquitination databases record sites on it; its protein half-life has been measured.
Gene: Protein-coding gene on chromosome 1 (71,395,943 to 72,282,539, reverse strand). Ensembl gene ENSG00000172260.
Subcellular location: Cell membrane
Subcellular location (Human Protein Atlas): Actin filaments; Cytosol; Vesicles
Pathways (Reactome):
Metabolism of proteins: Post-translational modification: synthesis of GPI-anchored proteins
Gene Ontology:
Molecular function: protein binding; transmembrane transporter binding
Biological process: cholesterol homeostasis; protein localization to plasma membrane raft; protein secretion; regulation of protein stability; heterophilic cell-cell adhesion; regulation of synapse assembly; negative regulation of glial cell proliferation; negative regulation of synapse assembly
Cellular component: late endosome; plasma membrane; extracellular region; postsynaptic density; apical dendrite; dendrite; dendritic shaft; dendritic spine; neuronal cell body
Genetic constraint (gnomAD): Loss-of-function variants: 5 observed, 24.53 expected, observed/expected ratio (o/e) 0.2, 90% interval 0.11 to 0.43. The upper end of that interval is the gene's LOEUF score, 0.43, which puts it in group 1 of 6, group 1 being the genes least tolerant of losing a copy. Missense variants: 218 observed, 286.27 expected, observed/expected ratio (o/e) 0.76, 90% interval 0.68 to 0.85. Synonymous variants: 124 observed, 113.29 expected, observed/expected ratio (o/e) 1.09, 90% interval 0.94 to 1.27.
Homologues: Orthologues: chimpanzee NEGR1 (100% identical), macaque NEGR1 (99% identical), rabbit NEGR1 (99% identical), pig NEGR1 (99% identical), guinea pig NEGR1 (97% identical), mouse Negr1 (94% identical), rat Negr1 (94% identical), dog NEGR1 (86% identical), tropical clawed frog negr1 (83% identical), zebrafish negr1 (61% identical), Drosophila melanogaster klg (29% identical), Drosophila melanogaster DIP-iota (28% identical), and 11 more. Paralogues in human: LSAMP (53% identical), NTM (46% identical), OPCML (46% identical), IGLON5 (39% identical), IGSF5 (16% identical).
Diseases named in the same sentence as NEGR1 in open-access papers:
NEGR1 is named in the same sentence as 78 diseases in open-access papers, as found by Europe PMC text mining. Sharing a sentence is not in itself a finding about the gene and the disease. The quoted sentences say what the papers report.
Obesity (87 papers, 2010 to 2026). Accumulation of substantial excess body fat. "Among these genes, the identification of NEGR1 as overlapping between AN and BMI (locus 2) is noteworthy, as NEGR1 is involved in neurodevelopment and has been associated with obesity, age at menarche and other psychiatric disorders." (PMID 39971893, 2025). "Although NEGR1 has been recognized as an obesity risk gene, recent large genome-wide association studies (GWAS) have identified NEGR1 as one of the most significant risk genes for major depressive disorders (MDD)." (PMID 40698360, 2025). "Genome-wide association studies have implicated NEGR1 as a risk factor for human diseases including obesity, autism, and depression, but its molecular function remains poorly understood." (PMID 40698360, 2025). "NEGR1 is associated with several human pathologies, including cancer, obesity, diabetes, neurodevelopmental disorders, depression, and ASD." (PMID 40698360, 2025). "Neuronal growth regulator 1 (NEGR1) is a brain-enriched membrane protein that has recently been recognized as a risk factor for many human diseases including obesity, depression, and autism." (PMID 37187893, 2023). "The association between NEGR1, obesity, and depression has been validated in independent human studies that cumulatively exceed 1.5 million individuals." (PMID 37111100, 2023). "The current study is the first to show alterations in the brain monoaminergic systems in Negr1-deficient mice, suggesting that monoaminergic neural circuits contribute to both depressive and obesity-related phenotypes linked to the human NEGR1 gene." (PMID 36552158, 2022). "Peculiarly, NEGR1 variations were reported to be associated with both obesity and the response to treatment with selective serotonin reuptake inhibitors (SSRIs)." (PMID 33905376, 2022). "In human GWAS studies, the neural adhesion molecule encoding the NEGR1 gene has been linked to both depression and obesity." (PMID 36552158, 2022). "Again, the data from mice supports the strong associations of the NEGR1 gene with both psychiatric and obesity-related phenotypes in human studies." (PMID 36552158, 2022). "Among the differentially expressed genes were neuroplastin (nptn), brain-derived neurotrophic factor (BDNF) and neuronal growth regulator 1 (Negr1)—genes associated with cognition, neuronal growth, plasticity and obesity." (PMID 35953488, 2022). "Supplementation of neuronal growth regulator 1 reverses this neurodegenerative effect, unveiling a neurotrophic role for this protein previously identified as a locus associated with human obesity." (PMID 36433953, 2022). "Altered monoaminergic neurotransmission has also been linked to both obesity and depression, and these conditions have been associated with neural pathways that are guided and maintained in the presence of NEGR1 protein." (PMID 36552158, 2022). "The trophic effect exerted by Negr1 on sympathetic neurites represents a promising mechanism for the impairment of energy metabolism associated with AT hypertrophy and obesity." (PMID 36433953, 2022). "NEGR1 is a generic risk factor for multiple human diseases, including obesity, autism and depression." (PMID 36142685, 2022). "In the past decade, Negr1 has gained increasing attention since it was identified as new locus associated with human obesity by three independent genome-wide association studies." (PMID 36433953, 2022). "Neuronal growth regulator 1 (NEGR1) is a candidate gene regulating human obesity, which encodes a neural cell adhesion and growth protein." (PMID 34572334, 2021). "We constructed a genetic risk score (GRS) based on five genetic variants (MC4R rs17782313, BDNF rs6265, FTO rs1421085, TMEM18 rs7561317, and NEGR1 rs2815752) and examined its association with obesity-related traits in a sample of Pakistanis." (PMID 33859285, 2021).
Obesity (continued). "Previously, it has been shown that mice with NEGR1 loss-of-function mutation (Negr1-I87N mice) exhibited decreased food intake but normal energy expenditure, thus fostering the positive association between NEGR1 expression and obesity." (PMID 34572334, 2021). "Dennis and colleagues reported that among 15 obesity-associated genetic variants, a variant in NEGR1 had the strongest effect on fractional anisotropy in the corona radiata in a sample of ~500 young, mainly normal-weight adults." (PMID 33100325, 2021). "In GWAS studies, NEGR1 gene locus has been repeatedly shown to have strong associations with human body mass index (BMI), indicating a role in body weight regulation and obesity." (PMID 34572334, 2021). "First, rs10889923 maps on an intron for NEGR1 (neuronal growth receptor 1), a very important gene many times linked to obesity, body mass index, triglycerides, cholesterol, etc. and many other phenotypes highly correlated with hypertension." (PMID 34296082, 2021). "Genotypic frequencies of the NEGR1 rs2815752 variant among gender-stratified cases (obese) and controls along with assessment of the association of the rs2815752 with obesity." (PMID 32419576, 2020). "NEGR1 (neuronal growth regulator 1 gene), a well-known obesity-associated gene, is associated with white matter integrity, and shows high expression in several brain tissues (highest median expression in frontal cortex)." (PMID 32373164, 2020). "The top two associations showed that a locus on FUT9 (rs4839813) associated with obesity, and rs1620977 on NEGR1 associated with morbid obesity with raw p-values p=2.3x10-5 and 2.8x10-5, respectively." (PMID 31888951, 2020). "Intriguingly, different polymorphisms in the Negr1 locus are also known to be associated with risk for body mass index and obesity." (PMID 32751911, 2020). "By keeping in view the entire aforesaid scenario, the current study was carried out to examine the association of the NEGR1 rs2815752 with overweight/obesity and obesity-related multiple traits in a sample of the Pakistani population." (PMID 32419576, 2020). "The study found a third of the transcripts to be differentially expressed between lean and obese siblings, with obesity-associated neuronal growth regulator 1 (NEGR1) acting as a central hub." (PMID 31823713, 2019). "Firstly, the sample size was insufficient to detect associations of obesity with low frequency alleles (1p31.1/NEGR1, 10q11.22/GPRC5B, and 16p12.3/NPY4R), although it was sufficient to find associations with 11q11/OR4P4/OR4S2/OR4C6, and 1p21.1/AMY1 CNs." (PMID 30388780, 2018). "As with most of the obesity‐associated genes, the function of Negr1 in the etiology of obesity is yet to be determined." (PMID 25077509, 2014). "In this study, we used AAV technology to increase and knockdown expression of the obesity‐associated gene Negr1 in the ARC/VMH and determine subsequent effects on the regulation of energy balance." (PMID 25077509, 2014). "Along with the strong association of the FTO locus, we also detected association of the SNP rs2815752 near the NEGR1 gene with severe obesity." (PMID 23950990, 2013). "In females, a variant at the NEGR1 locus also yielded nominal evidence of association with risk of obesity (OR = 3.15, 95% CI: 1.10–9.02, p = 0.018)." (PMID 23347264, 2013). "The obesity risk allele of the NEGR1 SNP associated significantly with lower fat intake (P = 3.2 × 10−5) but with higher carbohydrate (P = 3.3 × 10−5) and fiber intakes (P = 1.1 × 10−4)." (PMID 23861046, 2013). "This NEGR1 SNP ranked among the top four most strongly associated with extremes of obesity of all 32 BMI-associated loci in the GIANT analyses." (PMID 23950990, 2013). "The rs2815752 SNP is known to tag the 43 kb deletion, however the protective 8 kb deletion is the major driver of the association with extreme obesity at the NEGR1 locus and is tagged by an alternative SNP (rs1993709)." (PMID 23950990, 2013).
Obesity (continued). "Except for the NEGR1 gene, to our knowledge, the other neuronal genes are newly suggested in our research for the genetic association with obesity related traits." (PMID 21311593, 2011). "Similarly, on Mexican mestizos, researchers found a link between obesity and various genetic variants like NEGR1, MTCH2, and SEC16B which are also prevalent in other ethnic populations." (PMID 40024983, 2025). "Studies have suggested that some genetic loci, such as NEGR1 (neuronal growth regulator 1 gene, enables protein binding) or neural growth regulators, were associated with depression on the one hand and BMI and severe early-onset obesity on the other hand." (PMID 40930079, 2025). "Finally, we examined the effect of mutations in zebrafish orthologues of several genes associated with polygenic forms of obesity that previously showed some evidence of a causal role (i.e., NEGR1, SEC16B, ARID5B, IRS1, and IRS2)." (PMID 39948378, 2025). "Several GWASs have identified NEGR1 variants as risk factors for obesity and T2D susceptibility." (PMID 40141237, 2025). "This association with obesity suggested that the alterations in methylation detected in the loci of NEGR1 are related to BMI in general and may be important for weight regulation." (PMID 38849516, 2024). "Taken together, we propose that NEGR1 may play a regulatory role in IL-6 signaling by interacting with IL-6R, which may contribute to a molecular link underlying obesity, inflammation, and the depression cycle." (PMID 37187893, 2023). "We suggest that these neural circuits could underlay both depressive and obesity-related phenotypes that have been strongly linked with the NEGR1 gene in human studies." (PMID 36552158, 2022). "Here the authors use proteomics analysis on secretomes from perivascular fat to identify neuronal growth regulator 1 as an adipocyte-derived neurotrophic factor, whose decreased secretion in obesity results in a loss of sympathetic innervation of adipose depots in mice." (PMID 36433953, 2022). "Besides SNP markers, it has been found that two deletions (43 kb and 8 kb) upstream of NEGR1 are strongly associated with early onset of extreme obesity." (PMID 34572334, 2021). "Thus, according to a dominant genetic model, the GA/AA genotype of the NEGR1 rs2815752 variant increases 3.03-fold the odds of having obesity in females." (PMID 32419576, 2020). "However, the obesity results did demonstrate an increase in the genetic associations at the significance level of p<1x10-5 in and very close to the NEGR1 gene compared to previous BMI associations." (PMID 31888951, 2020). "A few SNPS had p-values suggestive of associations, including one obesity-related SNP, [rs2815752 (NEGR1), unadjusted p = 0.004] and several HTN-related SNPs [rs13139571 (GUCY1A3-GUCY1B3), rs11191548 (CYP17A1-NT5C2) and rs1801253 (ADRB1), each with unadjusted p = 0.01]." (PMID 31141530, 2019). "Our study has replicated known body composition loci including SEC16B, FTO and NEGR1 and resulted in the discovery of new signals that may associate with an increased risk for obesity-related traits." (PMID 30026463, 2018). "In addition, genetic variants in or near the NEGR1 locus have been associated with obesity and more recently with learning difficulties, intellectual disability and psychiatric disorders." (PMID 29479305, 2018). "Neural growth regulator 1 (Negr1) – also known as kilon or neurotractin – is among the first common variants that have been associated with body mass index (BMI), implicating Negr1 in the etiology of obesity." (PMID 25077509, 2014). "Notably, a recent GWAS analysis demonstrated an association of two deletions (43 kb and 8 kb) upstream of NEGR1 with early onset extreme obesity." (PMID 23950990, 2013). "Furthermore, two other loci, one close to the NEGR1 gene and another near STK33 were also associated to obesity in some studies and the NEGR1 gene has been independently associated with obesity in a pediatric cohort." (PMID 24267414, 2013).
Obesity (continued). "Since the GWAS discovery of this novel obesity locus, the association of the variants within NEGR1 loci has been replicated in various genotyping studies for body mass, BMI and other obesity-related traits such as birth weight, subcutaneous fat mass and infancy weight gain." (PMID 22844493, 2012). "While the expression of NEGR1 has been implicated as a central ‘hub’ in an obesity-related transcription network, immunoblotting analysis could not reveal expression of NEGR1 in wild-type subcutaneous white adipose tissue or tissues other than the brain." (PMID 22844493, 2012). "Similarly, the NEGR1 gene is associated with obesity and educational attainment." (PMID 41353206, 2025). "Lastly, researchers examined the NEGR1 rs2815752 variant and found 24 interactions between the risk allele “G” and random eating patterns, the tendency toward fat-dense food, inadequate and irregular sleep, and shift work, which increased all obesity parameters significantly." (PMID 39283705, 2025). "Indeed, NEGR1 has also been associated with obesity through GWAS." (PMID 37327674, 2023). "The current study is the first to explore the brain monoaminergic system in NEGR1-deficient mice to gain novel insights into whether these neural circuits could be responsible for the link between NEGR1 polymorphisms and phenotypes of depression and obesity." (PMID 36552158, 2022). "Differential co-expression analysis of obesity-associated networks in human subcutaneous adipose tissue revealed differential expression of the NEGR1 gene between normal-weight and obese siblings with identification of NEGR1 as a central hub in an obesity-related transcript network." (PMID 32419576, 2020). "Large-scale omics point out neuronal growth regulator 1 (NEGR1) as a main genetic link between obesity and depression." (PMID 41375608, 2025). "The 8 kb deletion removes the binding site for transcriptional repressor NKX6.1, leading to a higher Negr1 expression and lower odds of obesity." (PMID 39948378, 2025). "NEGR1 plays a crucial role in systemic metabolism, with circadian disruption contributing to obesity and glucose intolerance, particularly in the context of a high-fat diet." (PMID 40024983, 2025). "NEGR1 has been suggested to regulate cellular fat content via CD36 expression regulation, and its gene NEGR1 has been identified as a risk locus for obesity in genome‐wide association studies." (PMID 38420755, 2024). "Genome-wide association studies (GWAS) have identified an overlap between the genetic risk for depression and obesity through single-nucleotide polymorphisms near or in OLFM4 and NEGR1." (PMID 37111100, 2023). "They analyzed the five obesity-associated genetic variants (MC4R rs17782313, BDNF rs6265, FTO rs1421085, TMEM18 rs7561317, and NEGR1 rs2815752)." (PMID 35627568, 2022). "The 1p31.1 locus in the human genome, encoding the neuronal growth regulator 1 (NEGR1) gene, has been recently identified as one of the most significant risk loci for both depression and obesity." (PMID 36552158, 2022). "Of the identified genes in our study, FTO, GNPDA2, MC4R, MTCH2, NEGR1, SH2B1, TMEM18 are unequivocally regarded as obesity genes associated with PCOS, as supported by contemporary evidence." (PMID 35679284, 2022). "NEGR1 mediates neural cell communication and synapse formation, and its downregulation is related to obesity, learning difficulties, intellectual disability, and psychiatric disorders." (PMID 35207515, 2022). "In GWAS studies, the neural adhesion molecule encoding the neuronal growth regulator 1 (NEGR1) gene has been consistently linked with both depression and obesity." (PMID 36552158, 2022). "The “weight loss” group also showed decreased levels of APOE, C5, CRP, LBP, NEGR1, and PRSS3, which have all been positively associated with obesity, inflammation, and metabolic disorders (22, –, 26)." (PMID 34519531, 2021).